PPP3CA (protein phosphatase 3 catalytic subunit alpha)
Description:
Calcium-dependent, calmodulin-stimulated protein phosphatase which plays an essential role in the transduction of intracellular Ca(2+)-mediated signals. Many of the substrates contain a PxIxIT motif and/or a LxVP motif. In response to increased Ca(2+) levels, dephosphorylates and activates phosphatase SSH1 which results in cofilin dephosphorylation. In response to increased Ca(2+) levels following mitochondrial depolarization, dephosphorylates DNM1L inducing DNM1L translocation to the mitochondrion. Positively regulates the CACNA1B/CAV2.2-mediated Ca(2+) release probability at hippocampal neuronal soma and synaptic terminals (By similarity). Dephosphorylates heat shock protein HSPB1 (By similarity). Dephosphorylates and activates transcription factor NFATC1. In response to increased Ca(2+) levels, regulates NFAT-mediated transcription probably by dephosphorylating NFAT and promoting its nuclear translocation. Dephosphorylates and inactivates transcription factor ELK1. Dephosphorylates DARPP32. May dephosphorylate CRTC2 at 'Ser-171' resulting in CRTC2 dissociation from 14-3-3 proteins. Dephosphorylates transcription factor TFEB at 'Ser-211' following Coxsackievirus B3 infection, promoting nuclear translocation. Required for postnatal development of the nephrogenic zone and superficial glomeruli in the kidneys, cell cycle homeostasis in the nephrogenic zone, and ultimately normal kidney function (By similarity). Plays a role in intracellular AQP2 processing and localization to the apical membrane in the kidney, may thereby be required for efficient kidney filtration (By similarity). Required for secretion of salivary enzymes amylase, peroxidase, lysozyme and sialic acid via formation of secretory vesicles in the submandibular glands (By similarity). Required for calcineurin activity and homosynaptic depotentiation in the hippocampus (By similarity). Required for normal differentiation and survival of keratinocytes and therefore required for epidermis superstructure formation (By similarity). Positively regulates osteoblastic bone formation, via promotion of osteoblast differentiation (By similarity). Positively regulates osteoclast differentiation, potentially via NFATC1 signaling (By similarity). May play a role in skeletal muscle fiber type specification, potentially via NFATC1 signaling (By similarity). Negatively regulates MAP3K14/NIK signaling via inhibition of nuclear translocation of the transcription factors RELA and RELB (By similarity). Required for antigen-specific T-cell proliferation response (By similarity). Dephosphorylates KLHL3, promoting the interaction between KLHL3 and WNK4 and subsequent degradation of WNK4. Negatively regulates SLC9A1 activity.
Synonyms: CALNA; CNA1; PPP2B; ACCIID; CALN; CALNA1; DEE91; IECEE; IECEE1
Tractability: Small molecule: it belongs to a druggable protein family. Antibody: UniProt places it where antibodies can reach, with high confidence; its Gene Ontology location is reachable by antibodies, with high confidence. PROTAC: ubiquitination databases record sites on it; its protein half-life has been measured; a small molecule that binds it is known. Other modalities: an approved drug acts on it.
Target class: Protein Phosphatase; Phosphatase; Serine/threonine protein phosphatase; Enzyme
Gene: Protein-coding gene on chromosome 4 (101,023,409 to 101,348,278, reverse strand). Ensembl gene ENSG00000138814.
Subcellular location: Cytoplasm; Cell membrane; Cell membrane, sarcolemma; Cytoplasm, myofibril, sarcomere, Z line; Cell projection, dendritic spine
Subcellular location (Human Protein Atlas): Cytosol; Calyx; Nucleoplasm
Pathways (Reactome):
Immune System: CLEC7A (Dectin-1) induces NFAT activation; Calcineurin activates NFAT; FCERI mediated Ca+2 mobilization
Signal Transduction: Ca2+ pathway; DARPP-32 events
Gene Ontology:
Molecular function: ATPase binding; calmodulin binding; calmodulin-dependent protein phosphatase activity; enzyme binding; protein binding; protein dimerization activity; protein serine/threonine phosphatase activity; calcium ion binding; hydrolase activity
Biological process: calcineurin-mediated signaling; calcineurin-NFAT signaling cascade; negative regulation of angiotensin-activated signaling pathway; positive regulation of cell adhesion; positive regulation of cell migration; positive regulation of transcription by RNA polymerase II; protein dephosphorylation; response to calcium ion; dephosphorylation; epidermis development; keratinocyte differentiation; modulation of chemical synaptic transmission; negative regulation of calcium ion import across plasma membrane; negative regulation of signaling; positive regulation of activated T cell proliferation; positive regulation of calcineurin-NFAT signaling cascade; positive regulation of calcium ion import across plasma membrane; positive regulation of calcium ion-dependent exocytosis of neurotransmitter; positive regulation of glomerulus development; positive regulation of osteoblast differentiation; positive regulation of osteoclast differentiation; positive regulation of saliva secretion; regulation of cell proliferation involved in kidney morphogenesis; renal filtration; skeletal muscle fiber development; and 3 more
Cellular component: calcineurin complex; cytoplasm; cytoplasmic side of plasma membrane; cytosol; dendritic spine; plasma membrane; extrinsic component of plasma membrane; nucleoplasm; protein serine/threonine phosphatase complex; sarcolemma; Z disc
Genetic constraint (gnomAD): Loss-of-function variants: 7 observed, 54.18 expected, observed/expected ratio (o/e) 0.13, 90% interval 0.072 to 0.24. The upper end of that interval is the gene's LOEUF score, 0.24, which puts it in group 1 of 6, group 1 being the genes least tolerant of losing a copy. Missense variants: 281 observed, 577.26 expected, observed/expected ratio (o/e) 0.49, 90% interval 0.44 to 0.54. Synonymous variants: 203 observed, 205.55 expected, observed/expected ratio (o/e) 0.99, 90% interval 0.88 to 1.11.
Gene-disease validity (ClinGen):
ClinGen rates the evidence that PPP3CA causes each of these diseases.
developmental and epileptic encephalopathy (autosomal dominant): Definitive. An epilepsy associated with developmental impairment that may be due to either the underlying etiology or the superimposed epileptic activity, or both.
Homologues: Orthologues: chimpanzee PPP3CA (100% identical), macaque PPP3CA (100% identical), mouse Ppp3ca (99% identical), pig PPP3CA (99% identical), dog PPP3CA (99% identical), rabbit PPP3CA (97% identical), guinea pig PPP3CA (97% identical), rat Ppp3ca (97% identical), tropical clawed frog ppp3ca (95% identical), Caenorhabditis elegans C27B7.6 (27% identical), Drosophila melanogaster PpD5 (24% identical), Caenorhabditis elegans gsp-2 (24% identical), and 25 more. Paralogues in human: PPP3CB (83% identical), PPP3CC (78% identical), PPEF2 (26% identical), PPP1CA (25% identical), PPP1CC (25% identical), PPP2CA (25% identical), PPP2CB (25% identical), PPP1CB (24% identical), PPEF1 (23% identical), PPP4C (23% identical), PPP5C (22% identical), PPP6C (22% identical).
Diseases named in the same sentence as PPP3CA in open-access papers:
PPP3CA is named in the same sentence as 96 diseases in open-access papers, as found by Europe PMC text mining. Sharing a sentence is not in itself a finding about the gene and the disease. The quoted sentences say what the papers report.
cardiac hypertrophy (17 papers, 2010 to 2025). "This approach represents the successful design of a Cond-siRNA targeting CaN A-a (Ppp3ca), a key gene involved in pathological cardiac hypertrophy." (PMID 40861898, 2025). "Ppp3ca has been shown to be a key regulator of cardiac hypertrophy through activation of the transcription factor NFAT (nuclear factor of activated T-cells) which promotes the expression of pro-hypertrophic genes in concert with other transcription factors such as GATA4 and MEF2." (PMID 20937113, 2010). "MiR-99b targets protein phosphatase 3 catalytic subunit alpha (PP3CA), also known as calcineurin Aα, involved in cardiac hypertrophy and electrical remodeling." (PMID 33573156, 2021).
epilepsy (7 papers, 2017 to 2025). A brain disorder characterized by episodes of abnormally increased neuronal discharge resulting in transient episodes of sensory or motor neurological dysfunction, or psychic dysfunction. "The novel calcineurin A (Ppp3ca) variant associated with epilepsy, exhibits constitutive enzyme activation and the downregulation of protein expression." (PMID 40167866, 2025). "p.His92Arg, p.Asp234Glu Glu282Lys, and p.Ser419Cysfs*31were common variants among patients with PPP3CA-related epilepsy." (PMID 40548073, 2025). "Several studies have shown that variants in PPP3CA lead to epilepsy." (PMID 39823480, 2025). "Over 60% of PPP3CA variants in patients with epilepsy were located in the RD." (PMID 40548073, 2025). "Pathogenic or likely pathogenic of PPP3CA variants were identified in 15 children with epilepsy." (PMID 40548073, 2025). "This hypothesis is supported by the fact that mutations in Dlg3, Psen1, Dnm1, and Ppp3ca have been found in epilepsy patients." (PMID 32033586, 2020). "Mutations in PPP3CA may lead to neurodevelopmental disorders and epilepsy." (PMID 38200081, 2024). "In 21 patients with PPP3CA-related epilepsy reported in the literature, the age of seizure onset ranged from 1.5 months to 13 years, with 57.1% (12/21) experiencing their first seizure before the age of one." (PMID 40548073, 2025). "Therapeutic information for PPP3CA related epilepsy is limited." (PMID 40548073, 2025). "Secondly, this study demonstrated the genotype-phenotype correlation of PPP3CA-related epilepsy." (PMID 40548073, 2025). "This suggests that IESS is the most common phenotype of PPP3CA-related epilepsy." (PMID 40548073, 2025). "Most patients with PPP3CA-related epilepsy were drug-resistant." (PMID 40548073, 2025). "The brown module has 53 hub genes, including genes associated with dopaminergic signaling (GNB1, GSK3B), long-term potentiation (PPP1CB), opioid signaling (PPP2CA, PPP3CA, PPP3R1), epilepsy (SYN1), and Parkinson’s disease (SNCA)." (PMID 28710498, 2017). "However, other patients with PPP3CA-related epilepsy showed no significant response to ASMs." (PMID 40548073, 2025).
pancreatic cancer (5 papers, 2017 to 2025). "In recent years, it has been reported that PPP1CA, PPP1CB, PPP2CA, PPP2CB, and PPP3CA accelerate the progression of pancreatic cancer, while PPP3CB, PPP5C, and PPP6C hinder PAAD progression." (PMID 34125004, 2021). "More importantly, PPP3CA-NFATs pathway is reported to be crucial in pancreatic cancer growth and invasion." (PMID 28881575, 2017). "In addition, only PPP3CB and PPP6C showed favorable prognostic values with regard to protein level, whereas PPP1CA, PPP1CB, PPP1CC, PPP2CA, PPP2CB, and PPP3CA showed unfavorable prognostic values in pancreatic cancer (P<0.05)." (PMID 33270085, 2021). "Results of the present study suggest that PPP1CA, PPP1CB, PPP2CA, PPP2CB, and PPP3CA have deleterious effects but PPP3CB, PPP5C, and PPP6C have beneficial effects on pancreatic cancer." (PMID 33270085, 2021). "Intriguingly, our work showed that PPP3CA was an unfavorable prognostic factor, but PPP3CB was a favorable prognostic factor for pancreatic cancer." (PMID 33270085, 2021). "Data from THPA and patients with pancreatic cancer enrolled in our hospital also confirmed the prognostic value of PPP1CA, PPP1CB, PPP2CA, PPP2CB, PPP3CA, PPP3CB, and PPP6C at the protein level." (PMID 33270085, 2021). "Among all the PPPcs, the transcription levels of PPP1CA, PPP1CB, PPP3CA, PPP3CB, and PPP4C were higher in pancreatic cancer than in the normal pancreas." (PMID 33270085, 2021).
Epileptic encephalopathy (4 papers, 2017 to 2025). A condition in which epileptiform abnormalities are believed to contribute to the progressive disturbance in cerebral function. "In PPP3CA gene for protein phosphatase 3 catalytic subunit alpha, lof and gof variants lead to early onset epileptic encephalopathy and multiple congenital abnormalities, respectively." (PMID 36140794, 2022). "Interestingly, PPP3CA has just been recently identified as a novel epileptic encephalopathy gene." (PMID 29262854, 2017).
schizophrenia (4 papers, 2010 to 2022). A major psychotic disorder characterized by abnormalities in the perception or expression of reality. "Their results indicated that protein phosphatase 3 catalytic subunit alpha (PPP3CA) is the shared susceptibility locus for IBD (Crohn’s disease and ulcerative colitis) and schizophrenia." (PMID 36289839, 2022).
Alzheimer disease (3 papers, 2012 to 2017). A progressive, neurodegenerative disease characterized by loss of function and death of nerve cells in several areas of the brain leading to loss of cognitive function such as memory and language. "In the Alzheimer’s disease pathway, we found genes up-regulated (Apbb1, Atf6, Cacna1d, Calm3, Casp7, Itpr1, Lpl, and Ppp3ca) and down-regulated (Aph1b, Bid, Cycs, Fadd, Fas, and Nae1)." (PMID 28513549, 2017). "Ppp3ca is a tumor suppressor gene that functions in Alzheimer’s disease." (PMID 24555847, 2014).
breast carcinoma (3 papers, 2019 to 2022). "The alterations of PPP1CA, PPP3CA, PPP3CB and PPP6C were significantly associated with the prognosis of breast cancer." (PMID 34964699, 2022). "Furthermore, PPP3CA expression has been reported to be elevated in breast cancer 39, lung cancer 40, and prostate cancer." (PMID 31417643, 2019). "PPP2CB, PPP3CA, PPP3CB, PPP3CC and PPP6C were significantly expressed at lower levels in breast cancer tissues." (PMID 34964699, 2022). "In the Oncomine database, when compared with normal breast tissues, PPP1CA, PPP2CA, PPP4C and PPEF1 were significantly elevated in breast cancer tissues, while PPP1CB, PPP2CB, PPP3CA, PPP3CB, PPP3CC and PPP6C were significantly decreased in breast cancer tissues." (PMID 34964699, 2022).
multiple myeloma (3 papers, 2019 to 2024). "Aberrant expression of PPP3CA has also been observed in advanced multiple myeloma (MM), suggesting a potential association between elevated levels of PPP3CA and MM pathogenesis." (PMID 39103807, 2024). "Accordingly, we discovered PPP3CA as a novel target for MM and revealed that panobinostat suppresses myeloma cell growth through the degradation of this protein, which is released from over-acetylated HSP90." (PMID 30987296, 2019). "Another HDAC6 inhibitor panobinostat, which is used as an anticancer drug for multiple myeloma (MM), combined with FK506 significantly affected osteoclast formation through the reduction of PPP3CA expression." (PMID 36986544, 2023).
ovarian carcinoma (3 papers, 2019 to 2024). A malignant neoplasm originating from the surface ovarian epithelium. "Based on these findings, we suggest that CN-related poor overall survival may be due to the mutation of PPP3CA gene in unique subtype of ovarian cancer." (PMID 31399054, 2019). "Kaplan-Meier curve presenting the overall survival of ovarian cancer exhibiting high or low PPP3CA (a catalytic subunit of CN) expression." (PMID 31399054, 2019). "VPS13B, TBC1D22A, PPP3CA, CUX1 and PPP1R15A were identified as poor prognostic genes for cisplatin resistance in ovarian cancer, while PLGRKT, CDKAL1 and TAP1 were identified as good prognostic genes." (PMID 39103807, 2024). "The expression levels of VPS13B, TBC1D22A, PPP3CA, CUX1, and PPP1R15A genes were found to be up-regulated in ovarian tissue of cisplatin-resistant ovarian cancer patients compared to those with ovarian cancer." (PMID 39103807, 2024). "Through biological information screening, RT-qPCR and WB verification, it was found that VPS13B, TBC1D22A, PPP3CA, CUX1 and PPP1R15A were highly expressed in cisplatin-resistant tissues of ovarian cancer, while PLGRKT, CDKAL1 and TAP1 were low expressed." (PMID 39103807, 2024). "VPS13B, TBC1D22A, PPP3CA, CUX1 and PPP1R15A were identified as poor prognostic genes of cisplatin resistance in ovarian cancer, while PLGRKT, CDKAL1 and TAP1 were identified as good prognostic genes." (PMID 39103807, 2024).
cognitive deficits (2 papers, 2013 to 2020). "Both loss and gain of function manipulations to these activity-regulated genes, including Arc, Bdnf, Reln, Egr1 and Ppp3ca, have been associated with cognitive deficits during physiological aging and pathological conditions like dementia, neurodegenerative diseases and neuropsychiatric problems." (PMID 33013350, 2020).
colon cancer (2 papers, 2014 to 2022). "Among them the Src family member YES1 has been reported as a direct miR-145 target that plays oncogenic function in colon cancer, FSCN1 and PPP3CA are also directly regulated by this miRNA in esophageal squamous cell carcinoma and urothelial carcinoma." (PMID 25069957, 2014).
colorectal cancer (2 papers, 2022). A primary or metastatic malignant neoplasm that affects the colon or rectum. "In addition, we show that protein phosphatase 3 catalytic subunit alpha (PPP3CA) is essential for the expression and phosphorylation of NFATc4 caused by Camta1 knockdown, as well as the proliferation, invasion, and chemoresistance of colorectal cancer cells." (PMID 35332122, 2022). "Further functional studies are required to understand the roles of CMATA1 and NFATc4, as well as PPP3CA, in colorectal cancer." (PMID 35332122, 2022). "In order to further clarify the mechanism of action of CAMTA1/NFATc4 in oxaliplatin resistance in colorectal cancer, we analyzed the interaction between PPP3CA, CAMTA1, and NFATc4." (PMID 35332122, 2022). "Interestingly, NFATC4 knockdown can reverse the chemoresistance of CAMTA1-silenced colorectal cancer cells to oxaliplatin, and this cellular event is partly mediated by an interacting protein, PPP3CA, which together with CAMTA1, competitively binds to NFATc4." (PMID 35332122, 2022). "To determine whether CAMTA1, NFATc4, and PPP3CA interact in colorectal cancer cells, we performed qPCR, western blotting, and co-immunoprecipitation experiments." (PMID 35332122, 2022).
Hypoglycemia (2 papers, 2016 to 2021). A decreased concentration of glucose in the blood. "In control subjects, HSPB1, SMAD3 and HSPA1A decreased significantly, whilst MAPKAPK5 increased significantly in controls from baseline to hypoglycemia whilst, in T2D, PPP3CA increased and EPHA2 decreased." (PMID 34426634, 2021).
leukemia (2 papers, 2016 to 2026). A malignant (clonal) hematologic disorder, involving hematopoietic stem cells and characterized by the presence of primitive or atypical myeloid or lymphoid cells in the bone marrow and the blood. "Some of the PPP3CA interactor proteins implicated in leukemia pathobiology such as BCL11b, NPM1, GSK3β and Rb were further validated in Jurkat T-ALL cells expressing constitutively active PPP3CA*." (PMID 27304189, 2016). "Importantly, several proteins implicated in leukemia pathobiology emerged amongst the novel PPP3CA interactors such as Rb, NPM1, BCL11b, GSK3β and KDM1 (also known as LSD1)." (PMID 27304189, 2016). "Interestingly, several proteins implicated in leukemia pathobiology emerged amongst the novel PPP3CA interactors such as NPM1, BCL11b, GSK3β and KDM1 (also known as LSD1)." (PMID 27304189, 2016). "Importantly, using a drug-repurposing approach, we found that inhibition of CA5B, PPP3CA, and PP2A by acetazolamide, tacrolimus, and LB-100, respectively, showed high toxicity toward KMT2A::AFF1+ leukemic blasts and reduced leukemia burden in vivo." (PMID 42038742, 2026).
lung adenocarcinoma (2 papers, 2019 to 2020). A carcinoma that arises from the lung and is characterized by the presence of malignant glandular epithelial cells. "Recent study reported that a novel significantly mutated gene PPP3CA in lung adenocarcinoma, but not in lung squamous cell carcinoma." (PMID 31399054, 2019).